IL1B (interleukin 1 beta)
Diseases named in the same sentence as IL1B in open-access papers (continued):
Sharing a sentence is not in itself a finding about the gene and the disease.
Sepsis (continued). "In the NLRP3/IL-1β pathway, IL-1β and IL-18 are generally considered critical triggers of lung dysfunction during sepsis." (PMID 34599154, 2021). "The mRNA and protein expressions of IL-1β and IL-6, two main pro-inflammatory factors, were both higher in mice with sepsis than in the sham group." (PMID 34430706, 2021). "The statistical analysis indicated that, compared with those in the sham group, IL-1β, TNFα, IL-6, and IFNγ levels in the Sepsis group were upregulated, while SOD and GSH-PX levels were downregulated." (PMID 34489703, 2021). "Previous studies on myocardial dysfunction during sepsis underlined the role played by the cytokine storm, especially by TNF-α and IL-1β in inducing a precocious decrease in myocardial contractility." (PMID 34696451, 2021). "In our study, the animals with sepsis developed proinflammatory profiles that were characterized by increased expression of IL-1β, IL-10, IL-6 and TNF-α." (PMID 33676566, 2021). "Sepsis patients exhibited significantly higher expression and production of NLRP3 and the proinflammatory cytokines (TNF-α, IL-6 and IL-1β) than healthy controls, and these levels were significantly increased with sepsis progression." (PMID 34172780, 2021). "EP was also found to inhibit cleavage of IL-1β and NLRP3 inflammasome activation in attenuation of microglial activation in a mice model of sepsis-associated encephalopathy." (PMID 34066647, 2021). "Signaling through the adaptor protein MYD88 (an essential transducer for IL-1B and Toll-like receptor pathways) and the subsequent IFN-I stimulation has been implicated in conditioning of MDSC differentiation during sepsis." (PMID 34721400, 2021). "The levels of the proinflammatory cytokines TNF-α, IL-1β, IL-6, IL-12p70, and IL-10 in the serum and in the lungs of the A. baumannii-derived sepsis mouse model treated with IOX1 were significantly reduced." (PMID 33536477, 2021). "For example, lnc‐KCNQ1OT1 negatively regulates inflammatory factors (including TNF‐α, IL‐1β, and IL‐6) in sepsis‐induced myocardial injury and intimal hyperplasia." (PMID 34761437, 2021). "In vivo, overexpression of LBH decreased the lung histological changes, lung injury score, lung W/D ratio, expression of IL-1β, IL-6, and IL-18, and activation of NLRP3inflammasome in lung tissues of sepsis-induced ALI mouse model." (PMID 33553423, 2021). "Early clinical studies identified IL‐1β as a myocardial depressant factor that mediates HF in sepsis." (PMID 34472725, 2021). "In zebrafish with sepsis due to inoculation with S. pneumoniae with the morpholino directed against HIVEP1 was associated with increased mRNA expression of TNF-α, IL-1β, CXCL8a and CXCL8b, as well as enhanced mortality." (PMID 34804025, 2021). "Many experiments have shown that Era, an inhibitor of ferroptosis, can relieve sepsis induced by CLP or LPS in mice, which is associated with a reduced level of inflammatory cytokines such as tumor necrosis factor (TNF)-α, IL-1β, and HMGB1." (PMID 34482365, 2021). "In sepsis models, miR-128-3p overexpression decreased pro-inflammatory factors IL-6 and IL-1β’s expression as well as inhibited apoptosis indicator caspase-3 transcriptive activity." (PMID 34430706, 2021). "Interleukin-1b (IL-1b), as a serious pro-inflammatory cytokine, increases in the early stage of sepsis and is involved in the severity and evolution of organ dysfunction." (PMID 35237239, 2021). "In parallel, EPOR activation downregulated iNOS and IL-1β but increased Arginase-1 and shifted macrophage polarization into an anti-inflammatory stage, to properly balance against sepsis proinflammation." (PMID 34831360, 2021). "Yet, an inverse development has been observed in sepsis non‐survivors according to IL‐1β and G‐CSF demonstrating gradually increased values during the first 3 days from admission compared to sepsis survivors." (PMID 33719215, 2021).
Sepsis (continued). "For example, lncRNA MEG3-4 serves as a miRNA decoy that regulates IL-1β abundance to initiate and then limit inflammation to prevent sepsis during lung infection." (PMID 34026883, 2021). "TNF-α, IL-6, and IL-1β are all important proinflammatory factors, which play an important role in the occurrence and development of sepsis." (PMID 34721636, 2021). "We show that inhibition of the NLRP3/IL‐1β axis protects against systolic and diastolic dysfunction in sepsis." (PMID 34472725, 2021). "Studies have implicated that overproduction of IL-1β, IL-6, TNF-α, and IL-10 in mice and humans is associated with sepsis, and IFN-γ expression is enhanced persistently in patients who die of sepsis." (PMID 34612675, 2021). "In the present study, IL-1b and IL-10 levels had significant predictive value only in the group of patients with sepsis." (PMID 33917002, 2021). "In a sepsis model using lipopolysaccharide (LPS), injection of the N-glycan upregulated serum IL-10, and suppressed pro-inflammatory IL-1β, TNF-α and IFN-γ." (PMID 33727664, 2021). "The results showed that IL-1b enhanced the therapeutic effect of MSCs-Exo against sepsis by inducing macrophage polarization to an anti-inflammatory M2 phenotype." (PMID 35237239, 2021). "Excessive release of cytokines such as IL-1β and other inflammatory mediators synthesized and secreted by macrophages is the fundamental link of uncontrolled inflammatory response in sepsis." (PMID 34220338, 2021). "This study identified a possible signal pathway that activated NLRP3 Inflammasome to secrete IL-1β levels under sepsis conditions." (PMID 34584017, 2021). "Tumor necrosis factor alpha, IL-6, and IL-1β are significant pro-inflammatory factors, which can lead to and promote the occurrence and development of sepsis." (PMID 34616305, 2021). "The results showed that the levels of caspase-11, GSDMD-NT, NLRP3, ASC, caspase-1, IL-1β, and IL-18 were increased in sepsis mice and that ST pre-treatment suppressed this effect." (PMID 34483936, 2021). "In patients with severe sepsis and septic shock; IL‐1β, IL‐6, and G‐CSF have demonstrated good accuracy for predicting early mortality while IL‐6 and G‐CSF showed to be predictive of worsening of organ dysfunction." (PMID 33719215, 2021). "LPS is a known stimulator in the systemic inflammatory mechanism of sepsis, LPS-triggered ROS generation, and the release of inflammatory cytokines, such as IL-1β, TNF-α, IL-6, and IL-10." (PMID 33986684, 2021). "Previous study has found that HT can inhibit the expression of inflammatory factors such as TNF-α, IL-1β and IL-6, and attenuate infiltration of activated immune cells in LPS-mediated sepsis in mice." (PMID 34858184, 2021). "JMJD3 demonstrates promoting properties in sepsis by upregulating pro-inflammatory cytokines, IL-1β, and TNF-α expression." (PMID 33413595, 2021). "Most prominently, IFN-γ is often more elevated in patients with cytokine storm due to CAR T therapy than in patients with sepsis-induced cytokine storm, who often have higher levels of circulating IL-1β." (PMID 33397398, 2021). "The reduced pathology of sepsis-caused ALI was correlated with reduced levels of pro-inflammation cytokines such as TNF-α, IL-6 and IL-1β in blood and their mRNA transcriptional level directly in lung tissue." (PMID 33842398, 2021). "Plasma levels of CitH3, MPO and IL-1β were elevated in sepsis but were ameliorated by KYNA and its synthetic analogues." (PMID 34475875, 2021). "More importantly, N protein aggravates lung injury, accelerates death in sepsis and acute inflammation mouse models, and promotes IL-1β and IL-6 activation in mice." (PMID 34341353, 2021). "More recently, studies have been conducted that focus on inhibiting IL-1β to counteract the cytokine storm using Anakinra, an IL-1β antagonist, which has been shown to radically improve the survival rates of patients with severe sepsis." (PMID 34829918, 2021).
Sepsis (continued). "Some of the most studied pro-inflammatory cytokines in the pathophysiology of sepsis are interleukin-1β (IL-1β) and tumor necrosis factor α (TNF-α), both released from activated macrophages." (PMID 33632243, 2021). "In the present study, upregulation of both TNF-α and IL-1β, the most extensively studied cytokines in sepsis pathophysiology, was noted in the liver, heart and lung tissues of rats in the S group, consistent with previous reports from other researchers." (PMID 34499695, 2021). "We therefore reasoned that inflammatory mediators, such as TNF-α, IL-1β, and IL-6, contained within the septic mesenteric lymph play an indispensable role in the lung injury induced by sepsis." (PMID 33145344, 2020). "Previous findings confirmed that the level of TNF-α, IL-1β, and IL-6 are elevated within 6 h in sepsis brain tissue and continually increased for 10 to 30 days." (PMID 32457609, 2020). "Pyroptosis, an inflammatory form of programmed cell death, is the initiating event of sepsis and results in immune imbalance by releasing IL-1β and IL-18 in the early stages." (PMID 32851082, 2020). "The expression levels of TNF-α, IL-1β, and IL-6 mRNA in the intestine, liver, and lung of the rats in the sepsis group increased significantly, compared with the control and sham surgery groups." (PMID 33145344, 2020). "The data from clinical studies of sepsis showed that the plasma concentrations of IL-1β, IL-6, IL-8, MCP-1, IL-10, and IL-4 were significantly higher in non-survivors when compared with survivors." (PMID 32153410, 2020). "Sepsis-related mediators, such as endotoxin and the pro-inflammatory cytokines IL-1β, IL-2, IL-6, TNF-α, and IFN-β, have been shown to induce high expression of iNOS." (PMID 33123008, 2020). "Studies have found that the release of inflammatory cytokines, such as tumor necrosis factor (TNF-α) and interleukins (IL-1β and IL-6) increases, and promotes many immunopathological processes in sepsis, which are often referred to as “cytokines storm”." (PMID 33584285, 2020). "IL-1β values decreased back to baseline levels on day 7, whereas increased levels of IL-18 were maintained in the serum during the first week of sepsis." (PMID 33613537, 2020). "In summary, Paeoniflorin and HSYA are key active compounds in XBJ for managing sepsis, protecting cardiac function, and controlling inflammation in the cardiac tissue partially by limiting the production of IL-6, IL-1β, and CXCL2." (PMID 33986658, 2020). "IL-1β is a cytokine that plays critical roles in inflammation and cardiac dysfunction during severe sepsis." (PMID 32015566, 2020). "The lysosomotropic compound NB 06 down-regulates the expression of pro-inflammatory cytokines (e.g., IL-1B, IL-6 and IL-23A in LPS-stimulated macrophages and desipramine protects against sepsis-induced cardiac dysfunction in a murine sepsis model." (PMID 32668803, 2020). "In the left ventricles, the expression of C3aR decreased significantly, whereas the expression of IL-1β increased during sepsis compared to sham-treated animals." (PMID 32410859, 2020). "Stimulation with LPS leads to increased secretion of pro-inflammatory cytokines, including IL-6, TNF-α, and IL-1β in the bloodstream, which are resulted from exacerbation of inflammation in patients with sepsis." (PMID 32079307, 2020). "A wealth of research has corroborated that inflammatory cell infiltration and proinflammatory cytokines, including TNF‐α, IL‐6 and IL‐1β, play a vital role in the pathological process of sepsis." (PMID 32881263, 2020). "IL-1β not only enhances both systemic and local inflammatory/immune responses but also leads to tissue injury in sepsis, by synergistically acting along with other cytokines." (PMID 32825174, 2020). "The jejunal tissue structure and serum levels of TNF-α and IL-1β were assessed to confirm sepsis induction." (PMID 33200654, 2020).
Sepsis (continued). "As observed in MERS, SARS-CoV-1, and COVID-19 patients it is understood that initially delayed but gradual increase in cytokines like IL-1β, IFN-γ, IL-6, IL-8, and IL-10 is the main cause of rapid sepsis progression." (PMID 33634060, 2020). "Among the pro-inflammatory cytokines studied during sepsis, IL-1β, IL-6, IL-12, and IL-17 are of crucial importance." (PMID 32895405, 2020). "LPS is a cytotoxic agent that can induce inflammatory response and increase the expressions of inflammatory factors TNFα, IL-6, IL-8 and IL-1β, leading to sepsis." (PMID 32484206, 2020). "As the level of IL1B mRNA was earlier revealed to be processed and accumulated in sepsis-induced platelets, that is why IL1B expression was parallelly studied that was substantially induced (p = 0.002) in the ex vivo sepsis samples." (PMID 32013235, 2020). "Recently, IL-1β priming was found to enhance the immunomodulatory properties of MSCs partially through sEV-mediated transfer of miR-146a in a mouse model of sepsis." (PMID 33317598, 2020). "Although TNF-α and IL-1β play major roles in the pathogenesis of sepsis in murine models, these cytokines have limited use as clinical markers for at-risk patients." (PMID 32826331, 2020). "They regulate at least two host responses during sepsis: maturation and secretion of the pro-inflammatory cytokines interleukin-1β (IL-1β) as well as IL-18 and induction of pyroptosis, a rapid lytic form of programmed cell death." (PMID 33613537, 2020). "In the liver, puerarin inhibited the transcription of inflammatory factor TNF-α, IL-6, and IL-1β and protected hepatocyte apoptosis in sepsis mouse models." (PMID 32457606, 2020). "LVEDP,-dp/dtmax, cTnI, CK-MB, tumor necrosis factor-α, interleukin(IL)-6, and IL-1β were upregulated in the rat model of sepsis." (PMID 32578720, 2020). "It is important to note that caspase-1 genetic deletion leads to suppressed IL-1β levels and confers a protective effect on murine sepsis models and improves the survival of mice." (PMID 32825174, 2020). "Nanjo Y. has suggested that the use of colistin sulfate (subcutaneously injected at 1.0 mg per mouse) can reduce the levels of TNF-α, IL-6 and IL-1β in LPS-induced sepsis mouse model and lead to decreased toxicity." (PMID 33551807, 2020). "By contrast, previous studies have demonstrated that the MSCs significantly reduced systemic cytokines and chemokines (IL-6, IL-1b, IL-10, KC, and CCL5) after 28 h of administration in the sepsis-associated inflammation mouse model." (PMID 32903481, 2020). "Other cytokines, such as IL-1β, IL-6, and IL-10, can be used for the diagnosis of sepsis and evaluating the inflammatory responses and the prognosis for ARDS patients." (PMID 32566670, 2020). "Our analysis focused on detecting statistical differences in levels of 6 cytokines associated with cytokine storm (IL-1β, IL-1RA, IL-6, IL-8, IL-18, and TNF-α) between patients with moderate COVID-19, severe COVID-19, and ARDS or sepsis." (PMID 32706339, 2020). "Firstly, LL-37 enhances the survival of CLP mice by reducing the macrophage pyroptosis that induces the secretion of pro-inflammatory cytokines (such as IL-1β) and augments inflammatory reactions in sepsis." (PMID 32825174, 2020). "The APOE mRNA and protein levels in septic patients were significantly lower than those of the healthy controls (p = 0.024 and p < 0.001, respectively), while the levels of TNF-α, IL-6, and IL-1β were elevated in sepsis patients." (PMID 32978453, 2020). "In sepsis, pyroptosis is a special form of programmed cell death, which is accompanied by release of multiple inflammatory compounds, including IL-18 and IL-1β." (PMID 33552058, 2020). "In sepsis, endotoxin stimulates the synthesis and release of various pro-inflammatory cytokines and factors, including TNFα, IL-1β, IL-6, Fas ligand (FasL), granzymes, etc., mainly by mononuclear macrophages." (PMID 32457606, 2020).
Sepsis (continued). "Serum levels of the inflammatory cytokines TNF-α and IL-1β were significantly increased (5-fold) in the sepsis group (p ≤ 0.05)." (PMID 33200654, 2020). "Administration of 5-MTP to another sepsis model i.e. cecum ligation and perforation model also reduces serum IL-1β and IL-6 to the basal level." (PMID 32635910, 2020). "Doxycycline ameliorated pulmonary inflammation in a murine polymicrobial sepsis model by decreasing levels of IL-1β, IL-6 and TNFα in plasma and lungs." (PMID 33142770, 2020). "Our primary goal was to directly compare levels of 6 inflammatory cytokines commonly associated with cytokine storm (IL-1β, IL-1RA, IL-6, IL-8, IL-18, and TNF-α) between severe COVID-19 patients and patients with ARDS or sepsis." (PMID 32706339, 2020). "For septicemia caused by V. vulnificus, such cytokines include tumor necrosis factor alpha (TNF-α), interleukin 1 beta (IL-1β), IL-6, and IL-8." (PMID 32380667, 2020). "We investigated cytokine regulation during febrile neutropenia in childhood cancer patients and found that three cytokines (IL-8, MCP-1, and IL-1β) increase during febrile neutropenia in an ex vivo sepsis model." (PMID 32519027, 2020). "As enabling an ATP-induced IL-1β release can prevent infection and fatal sepsis, we believe that we discovered one of the vital functions of APP and its peptides that contributed to their striking conservation during evolution." (PMID 32906646, 2020). "RAPA terminated the excessive inflammatory response by maintaining the integrity of the membrane of sepsis cell model and reducing the release of IL-1β and IL-18 from these immune cells, which are the pivotal inflammation mediators in sepsis." (PMID 32851082, 2020). "Studies indicate that proinflammatory cytokines/chemokines, such as TNFα, IL-6, IL-1β, or MCP-1, etc., released of from activated microglia are important mediators for sepsis-associated brain inflammation." (PMID 32070376, 2020). "Published concentrations of TNF-α, IL-1β, IL-17AF and IL-8 in infants with sepsis are inconsistent, with some studies reporting results similar to ours, and others reporting higher cytokine concentrations in septic infants." (PMID 32407417, 2020). "Significantly increased serum interleukin-6, tumor-necrosis-factor-alpha and interleukin-1-beta confirmed sepsis." (PMID 32661347, 2020). "It has been reported MEG3 can regulate IL-1β abundance to prevent sepsis during lung infection by acting as a decoy of miRNA." (PMID 32410866, 2020). "In earlier studies, we demonstrated increased NLRP3 and IL-1β expression in cardiomyocytes during sepsis in mice and substantial release of IL-1β from cardiomyocytes in presence of LPS and ATP or nigericin." (PMID 32410859, 2020). "Elevated concentrations of TNF-α and IL-1β are found in the serum of septic patients and are responsible for sepsis-related cardiac depression." (PMID 32908632, 2020). "OB depletion is in part caused by a significant increase of inflammatory factors like IL-1β, TNFα, and G-CSF during the inflammatory phase of sepsis, making OBs a possible target for sepsis treatment." (PMID 32082321, 2020). "In the present study, the expression of the IL-1β increased in left ventricles during sepsis as well, which was already demonstrated in hearts of septic rats and mice 8 h after CLP." (PMID 32410859, 2020). "Biomarkers of sepsis so far evaluated in horses include interleukin-1β (IL-1β), interleukin-10 (IL-10), interleukin-6 (IL-6), serum amyloid A (SAA), soluble CD14 (sCD14) and procalcitonin." (PMID 33148245, 2020). "Pro-inflammatory cytokines, such as interleukin (IL)-6, IL-1β, and tumor necrosis factor (TNF) α have been shown to contribute to sepsis-associated hepatocellular dysfunction." (PMID 30873161, 2019). "Our study demonstrated that the activation levels of NF-κB (p65), pro-caspase-1, pro-IL-1β, NLRP3, caspase-1 and IL-1β were increased after CLP/LPS+ATP, illustrating that the NLRP3/caspase-1/IL-1β signaling pathway participates in sepsis." (PMID 30779706, 2019).